NOS3 (nitric oxide synthase 3)
Diseases named in the same sentence as NOS3 in open-access papers (continued):
Sharing a sentence is not in itself a finding about the gene and the disease.
COVID-19 (16 papers, 2020 to 2025). A disease caused by infection with severe acute respiratory syndrome coronavirus 2. "Research on NOS3 gene polymorphisms has revealed an association between NOS3 rs2070744 (T786C) and the severity of COVID-19." (PMID 40142738, 2025). "The association of the T-786C polymorphism of the NOS3 gene (dpSNP: rs2070744) with the onset of COVID-19 was analyzed using binary logistic regression." (PMID 40573382, 2025). "Variants such as SOD2 rs4880, GSTP1, GSTO1, PON1, and NOS3 have been associated with reduced enzymatic activity, impaired detoxification of ROS, and worsened COVID-19 severity or post-acute sequelae." (PMID 41209585, 2025). "We found a trend for an association of NOS3 27-bp VNTR 4b/a genetic polymorphism with the disease course of COVID-19." (PMID 40142738, 2025). "In this study, we investigated the association between COVID-19 severity and NOS3 G894T and NOS3 27-bp VNTR 4b/a genetic polymorphisms." (PMID 40142738, 2025). "This study examined the association between COVID-19 severity and NOS3 genetic variations." (PMID 40142738, 2025). "The absence of this association may have been due to the multifactorial nature of COVID-19 progression, sample size limitations that interfered with statistical power, or the presence of other NOS3 gene polymorphisms or genes that might affect the endothelium." (PMID 40142738, 2025). "Interestingly, there is a statistically significant link between decreased COVID-19 mortality and the distribution of improved-productivity NOS3 haplotypes (the gene encoding for endothelial nitric oxide synthase)." (PMID 33604758, 2021). "The NOS3 genetic polymorphisms T(-786)C, 27-bp VNTR 4b/a, and G894T influence the NOS3 expression and/or activity; thus, considering the NOS3 role in the immune system defense against COVID-19, genetic polymorphisms may be associated with the course and severity of COVID-19." (PMID 40142738, 2025). "In the endothelium, NOS3 has a secretory effect on erythropoietin, which protects children and young adults from COVID-19." (PMID 40142738, 2025). "In turn, the alleles and genotypes of the NOS3 gene (T-786C, rs2070744) were not predictors of COVID-19 in the study population." (PMID 40573382, 2025). "The purpose of this study was to investigate polymorphic variants of the genes FGB (rs1800790), NOS3 (rs2070744) and TMPRSS2 (rs12329760) in patients with SARS-CoV-2 and to determine their role in the COVID-19 severity course against the background of antiviral therapy." (PMID 40573382, 2025). "In ECs obtained from deceased patients who had COVID-19, the arterial subtype also predominantly expressed F2R, S1PR1, and NOS3." (PMID 39066212, 2024). "Through network analysis, it was found that the core targets of GGQL in the treatment of COVID-19 comorbid with DM include AR, GSK3B, DPP4, F2, NOS3, and so on." (PMID 37933071, 2023). "NO by endothelial nitric oxide synthase (NOS3) is implicated in vascular smooth muscle relaxation and mediates vascular endothelial growth factor (VEGF)-induced angiogenesis in coronary vessels, which may explain the many complications occurring in COVID-19 patients." (PMID 35891565, 2022). "The top 5 targets were AR (degree = 93), GSK3B (degree = 70), DPP4 (degree = 52), F2 (degree = 43) and NOS3 (degree = 34), and their candidate targets may be the main targets of GGQL against COVID-19 comorbid with DM." (PMID 37933071, 2023). "A review article focused on the potential protective role of eNOS-derived nitric oxide to severe COVID-19 indicated a direct negative correlation between COVID-19 mortality and the percentage of NOS3 WT haplotype." (PMID 36009328, 2022).
depression (16 papers, 2007 to 2025). "The six predominant targets (TNFα, ESR1, TLR4, PTGS2, MMP9 and NOS3) have been well documented to associate with depression." (PMID 35626632, 2022). "The NOS3 gene is involved in the proliferation of neuronal precursors that might be associated with the pathology of depressive disorders." (PMID 32111088, 2020). "NOS3 is involved in the proliferation of neuronal progenitor cells, which might be implicated in the pathophysiology of depressive disorders." (PMID 17605790, 2007). "NOS3 (or endothelial NOS) regulates the synthesis of NO, which plays an important role in the pathogenesis of depression by modulating neurotransmitter systems, and blocking NOS activity might result in antidepressant effects." (PMID 36431060, 2022). "The node degrees of IL6, nitric oxide synthase 3 (NOS3), solute carrier family 6 member 4 (SLC6A4), estrogen receptor (ESR1), and tumor necrosis factor (TNF) were greater than 10, suggesting that these targets could play important roles in the effects of AL on depression." (PMID 36431060, 2022).
glaucoma (16 papers, 2010 to 2026). Increased pressure in the eyeball due to obstruction of the outflow of aqueous humor. "Polymorphisms in Nos3 increase risk for glaucoma, the leading cause of irreversible blindness worldwide." (PMID 39932792, 2025). "An early research focus was the role of the NOS3 (nitric oxide synthase 3) gene in mediating glaucoma risk." (PMID 37423164, 2023). "We therefore assessed the association of glaucoma with polymorphisms of NOS3 and CYBA previously associated with cardiovascular disease." (PMID 22919264, 2012). "We therefore aimed at assessing the relationship between glaucoma and the G894T and T-786C polymorphisms of NOS3 and the C242T CYBA polymorphisms in a Caucasian cohort." (PMID 22919264, 2012). "Importantly, polymorphisms in the NOS3 gene in humans, which encodes eNOS, has been associated with an increased risk of glaucoma." (PMID 37358489, 2023). "In addition, several association studies showed a positive association between glaucoma and polymorphisms in the NOS3 gene and in genes encoding caveolins 1 and 2, that modulate eNOS activity through regulation of their expression to the endothelial membrane." (PMID 36941667, 2023). "Notably, functional polymorphisms in the NOS3 gene that alter eNOS function/activity have been described in various complex diseases, including glaucoma." (PMID 31914149, 2020). "The relationship between NOS3 polymorphisms and glaucoma in Caucasians is poorly understood." (PMID 22919264, 2012). "However, in Caucasians there are only three studies on the impact of NOS3 polymorphism in primary open-angle glaucoma (POAG) and their results are conflicting." (PMID 22919264, 2012). "A key modifiable risk factor for glaucoma is intraocular pressure (IOP), which is regulated by NO — a product of nitric oxide synthase 3 (encoded by Nos3) — in Schlemm’s canal of the conventional outflow pathway." (PMID 39932792, 2025). "In a similar analysis, the associations of hypertension and cigarette smoking with POAG risk were also found to depend on NOS3 genetic polymorphisms, again suggesting that nitric oxide signalling may play an important role in mediating the effect of environmental risk factors on glaucoma risk." (PMID 37423164, 2023). "As is the case in glaucoma, global Nos3-KO mice have elevated IOP and reduced outflow facility." (PMID 39932792, 2025). "Importantly, these findings in mice translate to humans, where polymorphisms in the Nos3 gene associate with increased risk of elevated IOP and glaucoma in genetic linkage studies involving several populations." (PMID 39932792, 2025). "Endothelial NO, derived from endothelial nitric oxide synthase (NOS-3), may protect ganglion cells by causing vasodilation and increasing ocular blood flow in patients with glaucoma." (PMID 27433524, 2014). "The vasodilator properties of NO may also play a major role in the regulation of ocular perfusion and polymorphisms in the NOS3 and CYBA might contribute to vascular dysregulation observed in glaucoma." (PMID 22919264, 2012). "For our analysis we selected NOS3 and CYBA polymorphisms that have previously been associated with vascular disease and therefore determined the distribution of G894T and T-786C in NOS3 and C242T in CYBA in a large Caucasian glaucoma cohort." (PMID 22919264, 2012). "First, the study did not directly compare the NOS3 polymorphism distribution of glaucoma patients with sex- and age-matched controls, but rather relied on previously published distributions in the Caucasian population for comparison." (PMID 22919264, 2012). "NOS3 may play a role in the etiology of glaucoma; it is found in the human outflow pathway and the vasculature supplying retinal ganglion cells, which may affect the regulation of intraocular pressure (IOP) and blood flow to the optic nerve, respectively." (PMID 22025889, 2011). "Therefore, NOS3 could affect the phenotype of glaucoma patients, and a disease phenotype-stratified analysis of NOS3 in our NTG patients is required." (PMID 20309402, 2010).
glaucoma (continued). "It was shown that NOS-2 is absent in healthy patients, while NOS-1 and NOS-3 are upregulated in glaucoma patients." (PMID 25914734, 2015).
prostate carcinoma (16 papers, 2008 to 2025). A carcinoma that arises from epithelial cells of the prostate gland. "One gene uniquely identified by MultiNEP, the NOS3 gene, is a known prostate cancer-related gene and is associated with tumor angiogenesis, proliferation, and invasiveness." (PMID 37216914, 2023). "There is no biological or epidemiological data on the association between NOS3 promoter polymorphisms and prostate cancer." (PMID 18823560, 2008). "In conclusion, this is the first publication that demonstrates an association of the NOS3 promoter region polymorphisms with prostate cancer progression." (PMID 18823560, 2008). "This is the first publication that associates the promoter polymorphisms of the NOS3 gene with prostate cancer risk; however, other polymorphisms, such as the 894G>T (Glu298Asp) and the intron 4 have also been evaluated." (PMID 18823560, 2008). "OGG1-rs1052133 and NOS3-rs1799983 were associated with risk of low-grade prostate cancer." (PMID 35096612, 2021). "NOS3 gene promoter haplotypes, number of copies, and prostate cancer risk." (PMID 18823560, 2008). "MiR-543 and miR-584 in trophoblast cells and miR-335 in prostate cancer cells down-regulate NOS3 expression and reduce their migratory capability." (PMID 34199590, 2021). "The NOS3 seems to have an important role in vascular development, maintenance of the vascular tone and tumor growth in human prostate cancer (PCa)." (PMID 18823560, 2008). "SSCP conformation and haplotypic frequencies, clinical parameters and laboratory data of the NOS3 gene in peripheral blood of patients with prostate cancer and benign prostatic hyperplasia." (PMID 18823560, 2008). "MiR-335 targets the 3′-UTR of NOS3 mRNA in trophoblast cells and prostate cancer, and may significantly decrease the ability to migrate of these tumor cells." (PMID 34199590, 2021). "OGG1-rs1052133 was positively (CG/GG vs. CC: OR=1.32, 95% CI: 1.01-1.73) and NOS3-rs1799983 was inversely (per minor allele: p-trend=0.04) associated with risk of low-grade prostate cancer." (PMID 35096612, 2021). "Our preliminary reporter gene analysis demonstrated that NOS3 could not be directly transactivated by ERG in prostate cancer cells." (PMID 35526071, 2022). "The NOS3 transcript levels presented a bimodal behavior in tumor development and may be used as a biomarker together with the PCA3 marker for molecular staging of the prostate cancer." (PMID 18823560, 2008).
Hypercholesterolemia (14 papers, 2011 to 2025). An increased concentration of cholesterol in the blood. "Emerging data indicate that NOS3-knockout mice display hypercholesterolemia among other clinical traits of MS." (PMID 22164159, 2011).
hyperlipidemia (14 papers, 2010 to 2025). "NOS3−/− mice appeared hypertensive and presented fasting hyperinsulinemia, hyperlipidemia, and lower insulin-stimulated glucose uptake than wild-type mice." (PMID 33953784, 2021). "HMG-CoA reductase inhibitors are commonly used in the treatment of hyperlipidemia disorders but in addition have a plethora of vasculoprotective, anti-inflammatory and anti-fibrotic effects mediated by endothelial nitric oxide synthase (eNOS, NOS3)." (PMID 25435896, 2014).
dementia (12 papers, 2013 to 2025). Loss of intellectual abilities interfering with an individual's social and occupational functions. "In this regard, a previous study investigated the impact of the single nucleotide polymorphism (SNP) in endothelial nitric oxide synthase (NOS3) gene on the development of pathological substrates and incident dementia." (PMID 33408596, 2020). "However, no substantial correlation was found between APOE genotypes affecting the NOS3 genotype in AD and dementia." (PMID 38790243, 2024). "NOS3 is identified as a comorbid gene in both AD and dementia." (PMID 38790243, 2024). "The NOS3 gene is one of those associated with vascular regulation; however, it has not been considered as a potential risk factor for dementia." (PMID 32111088, 2020). "By increasing BDNF (brain-derived neurotrophic factor) serum concentration and inducing NOS-3 (nitric oxide synthase-3) activity resveratrol may have possible therapeutical effects on cognitive impairments and dementias especially in those characterized by defective cerebrovascular blood flow." (PMID 30469326, 2018). "GALK1, EPHB4, and NOS3 showed significant region-dependent differential expression, with higher expression in the DLPFC of dementia cases and more pronounced regional differences compared to controls." (PMID 40799764, 2025).
asthma (11 papers, 2005 to 2025). "In a study of the NOS3 27-bp VNTR 4b/a genotypes of patients with asthma in the United States, the three alleles, 4a, 4b, and 4c, were observed among non-African-American patients with asthma." (PMID 40142738, 2025). "Some NOS1 and NOS3 polymorphisms studied in various populations showed a positive correlation with atopy, total IgE concentration or sensitization to inhaled allergens (e.g., Dermatophagoides pteronyssinus) and a possible relationship with the risk of asthma." (PMID 34946286, 2021). "In rs7830, the relation depended on asthma status, suggesting that NOS3 genetic variation plays the most important role among all nitric oxide synthases in asthmatic adults." (PMID 34946286, 2021). "In conclusion, this study identified NOS2 and NOS3 polymorphisms associated with higher levels of EBC NO2–NO3 and FeNO, and evidenced a modifying effect of asthma status on the associations between NOS3 genetic variants and FeNO levels." (PMID 22590587, 2012). "SNPs (N = 121) belonging to NOS1, NOS2 and NOS3 genes were genotyped in 1277 adults from the French Epidemiological study on the Genetics and Environment of Asthma (EGEA)." (PMID 22590587, 2012). "In this study, we found that exposure to TRAP was associated with higher levels of FeNO and lower levels of DNA methylation in the promoter regions of the NOS3 gene at various lag periods in children with asthma living in a seaport-adjacent community with high density of diesel truck traffic." (PMID 33573660, 2021). "There was significant heterogeneity of NOS3 SNP effect on FeNO levels according to asthma status, with opposite allele effects between subjects with and without asthma." (PMID 22590587, 2012). "Exposure to TRAP was associated with higher levels of FeNO and lower levels of DNA methylation in the promoter regions of the NOS3 gene, indicating that DNA methylation of the NOS3 gene could be an important epigenetic mechanism in physiological responses to TRAP in children with asthma." (PMID 33573660, 2021).
colorectal cancer (10 papers, 2017 to 2025). A primary or metastatic malignant neoplasm that affects the colon or rectum. "This is consistent with the mutations previously identified by our group in colorectal cancer patients (Housein, Kareem & Salihi, 2021), in which several NOS3 and CTH gene mutations were discovered." (PMID 38107574, 2023). "Another research in mesenchymal colorectal cancer patients reported that NOS3 upregulation occurs after Apc loss, which was associated with poor prognosis." (PMID 33747912, 2021). "This was consistent with the observation that L-NIO (a NOS3 inhibitor) inhibited cell growth and angiogenesis in colorectal cancer." (PMID 33747912, 2021). "Furthermore, the NOS3 gene exhibited distinct mutations in the VNTR, T786C, and G894T genes in colorectal cancer." (PMID 38962618, 2024). "This study also demonstrated that hub genes (IL1B, GSK3B, NOS3, RELA, and CDK4) were most likely to be involved in the effects of oxidative stress brought on by geniposide in the prevention of colorectal cancer." (PMID 37894904, 2023). "Our PPI network analysis results showed that IL1B, GSK3B, NOS3, RELA and CDK4 were related to oxidative stress induced by geniposide against colorectal cancer." (PMID 37894904, 2023).
aneurysm (9 papers, 2015 to 2024). Bulging or ballooning in an area of an artery secondary to arterial wall weakening. "Taken together, higher MLDGS score may represent higher expression of IL1B, TLR4, VEGFA and MMP2, and lower expression of NOS3, implying inferior vascular stability at the molecular level and high risk of aneurysm rupture and CVS onset." (PMID 36844725, 2023).
aortic aneurysm (9 papers, 2012 to 2025). A ruptured aneurysm located in the wall of the proximal portion of the descending aorta proceeding from the arch of the aorta. "VSMCs of Nos3−/− mice showed downregulation of 15 genes, of which seven were associated with aortic aneurysms and dissections in the human population." (PMID 32801116, 2020). "This study examined the developmental processes involved in aortic aneurysm formation and found dissections in ∼13% of Nos3−/− mice aged from 1 to 11 months, of which 25% had a BAV." (PMID 32801116, 2020). "The variants in NOS3 identified in the current study may lead to less active NOS3 and as such may protect against development of aortic aneurysm." (PMID 28659821, 2017).
type 1 diabetes (9 papers, 2009 to 2025). "It is not clear how NOS3 may influence global DNA methylation, but a study involving obese children and type 1 diabetes with NOS3 polymorphisms demonstrated an improved endothelial function after supplementation with folate." (PMID 27990443, 2016). "In fact, we have shown a similar finding in a different population for the endothelial nitric oxide synthase gene where NOS3 gene polymorphisms, but not measures of circulating NO activity, were associated with arterial stiffness in children with type 1 diabetes." (PMID 23245743, 2012).
cerebrovascular disease (8 papers, 2011 to 2025). "A few literature reports have revealed that the NOS3 gene Glu298Asp (rs1799983) polymorphism is associated with an increased incidence of cardiovascular disorders and cerebrovascular diseases." (PMID 24602444, 2014). "Carriers of NOS3 Asp298, particularly if exposed to adverse environmental influences on endothelial function, may be at increased risk of developing cerebrovascular disease, including essential AH and pre-eclampsia." (PMID 33809023, 2021). "Currently, research on NOS3-targeted medicine is mainly concentrating on cardiovascular and cerebrovascular disease." (PMID 33747912, 2021).
Cognitive impairment (8 papers, 2007 to 2023). Abnormal cognition is characterized by deficits in thinking, reasoning, or remembering. "Among the significantly enriched signaling pathways from KEGG analysis, oxytocin signaling pathway (PATH:04921; Cacng2, Adcy1, Kcnj4, Kcnj9, Adcy8, Pik3cd, Elk1, Adcy4, Camkk2, Cacng7, Nos3, Kcnj2) may play an important role in the sevoflurane-induced cognitive impairment." (PMID 31582589, 2019).